POLG (DNA polymerase gamma, catalytic subunit)
Diseases named in the same sentence as POLG in open-access papers (continued):
Sharing a sentence is not in itself a finding about the gene and the disease.
POLG also shares sentences with these, for which no sentence is quoted: cerebellar ataxia (8 papers); Kearns-Sayre syndrome (5); Sensory neuropathy (5); dementia (4); Epileptic encephalopathy (4); MERRF (4); Myoclonus (4); ataxia telangiectasia (3); cerebrotendinous xanthomatosis (3); infantile-onset spinocerebellar ataxia (3); MELAS syndrome (3); myoclonic epilepsy (3); Osteopenia (3); Brain atrophy (2); coenzyme Q10 deficiency (2); developmental disability (2); dysautonomia (2); Dystonia (2); Hypergonadotropic hypogonadism (2); infantile spasms (2); metabolic disease (2); mood disorder (2); Neurodevelopmental delay (2); neuronal ceroid lipofuscinosis (2); Niemann-Pick disease type C (2); osteoporosis (2); progressive ataxia (2); Rett syndrome (2); Sensorineural hearing impairment (2); Spastic paraplegia (2).
A further 124 diseases each share a sentence with POLG in 1 paper.